CD36 (CD36 molecule (CD36 blood group))
Diseases named in the same sentence as CD36 in open-access papers (continued):
Sharing a sentence is not in itself a finding about the gene and the disease.
breast carcinoma (continued). "Despite consistent correlation in expression between CD36, LPL, PDK4, and FABP4 in all breast cancer subtypes (data not shown), the only subtype that displayed poorer survival was CL-TNBC (p = 0.0119; HR = 1.92)." (PMID 31942031, 2020). "However in breast cancers, it is the elevated expression of FABP5 rather than CD36 or FABP4 that play critical roles in acceleration of FA trafficking and nuclear activation of PPARγ, along with induction of lipolysis and ATGL-mediated utilization of accumulated lipids." (PMID 34888248, 2021).
steatosis (148 papers, 2008 to 2025). Increased lipid within the cytoplasm of cells. "CD36, situated in the hepatocyte plasma membrane, is associated with elevated steatosis, involving increased circulating FFA uptake and subsequent TAG storage in the liver." (PMID 40195072, 2025). "Our previous study found that increased CD36 expression has been linked to exacerbated steatosis by promoting hepatic fatty acid uptake and triglyceride storage." (PMID 40562101, 2025). "Further investigation into this possibility will be essential to fully elucidate the molecular mechanisms underlying CD36 downregulation and steatosis attenuation in S100a8-KO mice." (PMID 41178716, 2025). "Morphological examination and histological staining revealed that CD36 deficiency abrogated the increases in hepatic steatosis, inflammation and liver injury induced by SLC9A6‐126aa overexpression." (PMID 39107881, 2024). "Previously, we have shown that adult-onset hepatocyte-specific PPARγ knockout (PpargΔHep) mice showed reduced high-fat diet-induced steatosis associated with a reduction in hepatic CD36 expression and fatty acid uptake." (PMID 32411189, 2020). "Deletion of ACE2 causes CD36/sirtuin 1 axis impairment and thereby interferes with lipid homeostasis, leading to lipodystrophy and steatosis." (PMID 28101297, 2016). "CD36 expression in the liver is relatively low but levels are up-regulated under various conditions associated with steatosis." (PMID 20360851, 2010). "CD36, a high-affinity receptor for free FAs, is implicated in the onset of steatosis in MASLD." (PMID 40287434, 2025). "Interestingly, they identified CD36 as a new AHR target and linked steatosis-promoting AHR activation to increased expression of CD36 and lipid uptake into liver cells via CD36." (PMID 34075438, 2021). "CD36 reportedly facilitates uptake and intracellular trafficking of free fatty acids, and hepatic CD36 upregulation was shown to be associated with increased steatosis in human NASH24." (PMID 26818807, 2016). "In addition, hepatic CD36 upregulation has been shown to be associated with insulin resistance, hyperinsulinaemia, and increased steatosis in patients with non-alcoholic steatohepatitis and chronic hepatitis C." (PMID 24970143, 2012). "They think that CD36 deletion is protective for steatosis when the major cause is excessive FA uptake (high-fat diet), but might intensify lipid accumulation when hepatic lipogenesis is a major contributor to steatosis." (PMID 32796572, 2020). "However, subsequent studies have shown that CD36 is also associated with hepatic simple steatosis." (PMID 33344451, 2020). "Fatty acid translocase CD36 is recognized as a transcriptional target of AhR, as is PPARα, which mediates steatosis development." (PMID 41440753, 2025). "This decrease in steatosis correlated with decreased level of sterol regulatory element-binding protein-1c, reduced expression of the fatty acid transporter Cd36, enzymes involved in ceramide synthesis and proinflammatory markers." (PMID 41262214, 2025). "Studies have shown that overexpression of Cd36 enhances hepatic fatty acid uptake and fat accumulation, whereas liver‐specific knockout of Cd36 reduces hepatic lipid levels in both genetically induced and diet‐induced steatosis." (PMID 40195072, 2025). "Remarkably, this upregulation is further potentiated in the presence of Ex-4, implying the involvement of CD36 in the observed Ex-4-treated steatosis reduction." (PMID 40002783, 2025). "Elevated hepatic CD36 levels are observed in HFD-induced MASLD models, while hepatocyte-specific CD36 deletion attenuates fatty acid uptake and protects against steatosis." (PMID 41306774, 2025).
steatosis (continued). "Studies have shown that CD36 expression is upregulated in the liver with steatosis compared to healthy livers." (PMID 40562101, 2025). "Here, we demonstrate a novel role for NTS signaling in the initiation of steatosis by promoting lipid uptake through CD36 at the expense of bioenergetic capacity of hepatocytes." (PMID 40287434, 2025). "NORM3 also restored the protein expression of CPT1 to STD levels and consistently increased HFD‐altered expression of Ppara and reduced Cd36 and Fasn, both critical markers of steatosis." (PMID 39474783, 2024). "Expression of hepatic CD36, a fatty acid transporter correlated with the presence of macrovesicular steatosis, was decreased in DIO-MASH FGF15INT-KO mice." (PMID 38587078, 2024). "Early endotoxin challenge induced a marked alteration in the hepatic lipid metabolism of female WAG/Rij rats, reducing the mRNAs of PPAR-α, involved in the regulation of fatty acid oxidation (FAO) and increasing CD36, a key marker of steatosis." (PMID 39199203, 2024). "LOLA treatment strongly downregulated cd36 mRNA expression in the HepG2 models of steatosis and MetS." (PMID 38675168, 2024). "CD36 is a membrane receptor, and it is a known driver of hepato-steatosis onset, contributing significantly to its progression to NASH." (PMID 36831184, 2023). "Improved abnormal serum biochemical indicators TG, TC, LDL-C and glucose, inhibited lipid accumulation and steatosis; downregulated CD36 and SREBP-1C, upregulated CYP7A1." (PMID 36671814, 2023). "In both the animal and cell models of cellular steatosis used in this study, CD36 expression levels were elevated." (PMID 37764494, 2023). "For example, the downregulation of CD36 expression in the liver by MicroRNA-29 led to an attenuation of high fat diet induced steatosis along with a reduction in the expression of fibrotic markers including Col1a1." (PMID 38098035, 2023). "Wtap-HKO mice have abnormally raised CD36 levels, which contributes to the enhanced steatosis in both NC diet– and HFD-fed Wtap-HKO mice." (PMID 37777158, 2023). "Meanwhile, PPAR-γ directly regulates CD36 transcript levels, thus promoting hepatic lipid uptake and affecting lipid metabolism, resulting in hepatic lipid deposition and steatosis in NAFLD." (PMID 35784533, 2022). "Hepatic CD36 overproduction increases fatty acid intake, contributing to steatosis, whereas hepatic CD36 depletion protects against fat-induced steatosis in HFD-fed mice." (PMID 35700043, 2022). "As oxidized LDL is a ligand for CD36, it would bind to CD36 to increase lipid uptake in liver, contributing to steatosis." (PMID 36331958, 2022). "A positive correlation between plasma insulin levels and hepatic CD36 expression was observed in insulin-resistant patients with steatosis." (PMID 34327606, 2022). "The anti-steatosis effects of myeloid GPSM1 knockout were presumably attributed to downregulation of fatty acid uptake genes (CD36, FABP4) and upregulation of fatty acid β-oxidation genes (LCAD) in the liver." (PMID 36434066, 2022). "Adenoviral overexpression of CD36 increased hepatic lipid uptake and steatosis in mice fed a normal fat diet." (PMID 36148775, 2022). "The antitumor and immunosuppressive drug rapamycin was shown to reduce lipid accumulation in 3T3-L1 cells and improve hepatic steatosis by reducing CD36 expression in mice fed a high-fat diet." (PMID 36148775, 2022). "It has been shown that abnormally increased expression of CD36 contributes to the development of steatosis and NASH12, whereas knockout of Cd36 has been shown to protect against MCD-induced NASH13." (PMID 34893641, 2021). "A significant decrease in steatosis was observed in LPHs-treated mice, which presented a decreased gene expression of CD36 and LDL-R, crucial markers in MAFLD." (PMID 34439470, 2021). "Previous studies have demonstrated the pathogenic role of CD36 in rodents fed with HFD and a significant upregulation of CD36 associated with an increased steatosis in patients with NASH." (PMID 34439470, 2021).
steatosis (continued). "The transmembrane glycoprotein CD36 plays a fundamental role in the steatosis process providing the hepatic long-chain fatty acids uptake." (PMID 34439470, 2021). "On the contrary, liver-specific deletion of CD36 shows decreased hepatic lipid concentration in both genetic and diet-induced steatosis models." (PMID 33348908, 2020). "Since, MCD diets increase the expression of hepatic PPARγ and CD36 in mice, it is plausible that these genes contribute to the development of steatosis and the subsequent progression to NASH in mice fed with MCD diets." (PMID 32411189, 2020). "The hepatic inflammation indicator aspartate aminotransferase (AST) and positive regulator of hepatic steatosis CD36 corresponded with the histological findings." (PMID 32961796, 2020). "The elafin-dependent exosomal inhibition of steatosis and hepatic Cd36 mRNA expression was reversed by miR181b-5p and miR219-5p inhibitors." (PMID 32733043, 2020). "Deletion of CD36 in a mouse model fed with a high-fat diet improved steatosis and whole-body insulin sensitivity by lowering FA uptake; lowering the accumulation of TAGs, DAGs, and cholesterol esters; and reducing inflammation." (PMID 32796572, 2020). "Overall, these data suggested that MCD diets promoted steatosis and altered the composition of fatty acids in the liver independently of hepatocyte PPARγ or CD36 expression and hepatic fatty acid uptake." (PMID 32411189, 2020). "The disruption of hepatocyte-specific CD36 was shown to reduce liver lipid content and improve insulin sensitivity in high-fat diet-induced steatosis mice." (PMID 32443660, 2020). "Both PPARγ and CD36 contribute to the development of high-fat diet-induced steatosis in mice by upregulating steatogenic mechanisms that involve de novo lipogenesis (DNL) and fatty acid uptake." (PMID 32411189, 2020). "Under HFD, wild type mice develop steatosis and steatofibrosis and show an increased hepatic CD36 level, as well as elevated mtDAMPs and pro-inflammatory genes, while these phenotypes and markers are significantly reduced in miR-29aTg mice." (PMID 32331364, 2020). "In agreement with our findings in OSA patients, the majority of mice exposed to IH displayed simple steatosis as well as a higher hepatic TG content and CD36 expression than in control mice breathing normal oxygen concentrations." (PMID 32850919, 2020). "In the present study, we demonstrated that MCD-induced hepatic CD36 level and the presence of steatosis can be restored in the context of miR-29a overexpression, supporting miR-29a’s role in counteracting lipid accumulation." (PMID 32961796, 2020). "Mice fed with a high-fat diet (HFD) develop steatosis and present an increase in CD36 mRNA and protein expression." (PMID 33348908, 2020). "Another reason for the described inconsistencies in the perception of the role of CD36 is most likely the use different animal models of steatosis (other rodent species; genetic modifications or factors initiating steatosis)." (PMID 32796572, 2020). "The C57BL/6 mice harboring miR-29a overexpression presented reduced plasma AST, hepatic CD36, steatosis, and fibrosis induced by MCD." (PMID 32961796, 2020). "In the hepatic cellular model of steatosis, the expression of fatty acid transport (CD36) and lipogenesis (FAS) genes was inhibited in L-02 cells after 48 h cultured in the FFA mixture and treated with melatonin." (PMID 32093272, 2020). "The increase in steatosis, increased expression of CD36, SREBF1, and SCD1, and the decreased expression of CEACAM1 and GLUT2 are all key features also seen in our hyperglycemic HepG2 model as well as the Leprdb/J mouse model." (PMID 31805072, 2019). "Accompanying the observed steatosis, palmitic acid-induced lipid accumulation also leads to increased expression of CD36, SREBF1, and SCD1." (PMID 31805072, 2019).
steatosis (continued). "Lower severity of steatosis was found in S. spinosum-treated KK-Ay mice, accompanied with lower mRNA expression of CD36, a biomarker of atherogenesis and metabolic dysfunction as well as some others pro-inflammatory genes." (PMID 29768504, 2018). "Concomitant with reduced PPARγ2 expression, the expression of its steatosis target genes including CD36, FABP4 and PLIN2, CIDEC was also reduced." (PMID 30214048, 2018). "Expression of the transport gene CD36, the protein activity of which is crucial for development of steatosis in obese patients with liver disease, was significantly reduced by OCA." (PMID 30254132, 2018). "Reduced GH signaling in liver caused reduced Igf-1 expression and impaired growth, as well as increased levels of CD36 and Vldlr, which is consistent with the reported steatosis and altered lipid profile in the liver of Nestin-Cre mice." (PMID 26275221, 2015). "The fatty acid translocase CD36 was up-regulated at the protein level in both steatosis patient samples although only significantly in cells derived from patient H0008, thus suggesting an increased uptake of lipids in steatosis patients." (PMID 22969728, 2012). "CD36 deletion exacerbates steatosis by impairing hepatic triglyceride secretion in ob/ob mice." (PMID 40110132, 2025). "Up-regulation of CD36 induced by excess high fructose input mediates steatosis in MASLD." (PMID 40725208, 2025). "Hepatocytes or Kupffer cells specific deletion of CD36 alleviates steatosis in HFD-fed mice." (PMID 40110132, 2025). "Importantly, this study also reported the upregulation of CD36, a well-known fatty acid transporter, in both the in vitro model of steatosis and liver samples from MASLD patients and mice." (PMID 40959287, 2025). "Additionally, hepatic CD36 mRNA levels positively correlated with steatosis severity in obese insulin-resistant rats, emphasizing its role in hepatic lipid accumulation." (PMID 41440558, 2025). "Therefore, we overexpressed Klf2 in C36/− mice fed a normal diet and found that KLF2 induced steatosis as well as an increase in liver weight in CD36−/− mice in the fed stage." (PMID 37949368, 2024). "Moreover, in females, LPS increased the lipid transporter CD36, a crucial marker of steatosis responsible for the influx of fatty acids into the hepatocytes." (PMID 39199203, 2024). "Genes involved in steatosis (Cd36, Lpl), hepatoxicity (Avpr1a, Pla2g12a), necrosis (Serpine1), fatty acid metabolism (Acox1, Cpt1b, Cyp4a10, Ehhadh), lipid transport (Apoa1), and PPAR transcription factors (Pparδ) were altered with PFHpS exposure compared to vehicle-exposed animals." (PMID 39066581, 2024). "Furthermore, those observations were confirmed by qPCR examination of steatosis-related genes in which the expressions of CD36 and PPARγ were significantly changed accordingly with the DKK1 manipulations under HFD." (PMID 36410795, 2023). "The steatosis observed in CA-AhR transgenic mice was characterized by the enhanced uptake of fatty acids, increased hepatic oxidative stress, the elevated expression of CD36 and a reduction in VLDL triglyceride secretion." (PMID 38067179, 2023). "It suggests that the DKK1 promoted steatosis is CD36 dependent." (PMID 36410795, 2023). "We found that SZ-A inhibited CD36 and PPARγ mRNA expression and promoted PPARα mRNA expression, suggesting that SZ-A may decrease hepatic lipid accumulation and steatosis by inhibiting de novo lipogenesis and fatty acid uptake, while promoting β-oxidation." (PMID 35624769, 2022). "CD36 induces hepatosteatosis and may contribute to the development of NASH, and several clinical studies have shown that CD36 is closely associated with NAFLD patients and positively correlated with the degree of steatosis in the liver." (PMID 35743193, 2022). "CD36 deletion aggravates steatosis by impairing the secretion of hepatic TG and ApoB." (PMID 35405926, 2022).